DNAAF2 (dynein axonemal assembly factor 2)
Description:
Required for cytoplasmic pre-assembly of axonemal dyneins, thereby playing a central role in motility in cilia and flagella. Involved in pre-assembly of dynein arm complexes in the cytoplasm before intraflagellar transport loads them for the ciliary compartment.
Synonyms: C14orf104; KTU; FLJ10563; pf13; CILD10
Tractability: Antibody: its Gene Ontology location is reachable by antibodies, with medium confidence. PROTAC: ubiquitination databases record sites on it.
Gene: Protein-coding gene on chromosome 14 (49,625,174 to 49,635,244, reverse strand). Ensembl gene ENSG00000165506.
Subcellular location: Cytoplasm; Dynein axonemal particle
Subcellular location (Human Protein Atlas): Basal body; Cytosol; Golgi apparatus; Nucleoli; Primary cilium
Gene Ontology:
Molecular function: protein binding
Biological process: axonemal dynein complex assembly; cilium-dependent cell motility; epithelial cilium movement involved in extracellular fluid movement; protein stabilization
Cellular component: cytoplasm; cytosol; protein folding chaperone complex; dynein axonemal particle; extracellular region
Genetic constraint (gnomAD): Loss-of-function variants: 60 observed, 40.75 expected, observed/expected ratio (o/e) 1.47, 90% interval 1.19 to 1.81. The synonymous counts are far from expectation, so gnomAD's model fits this gene poorly and the ratio says little. Missense variants: 1,231 observed, 1,006.7 expected, observed/expected ratio (o/e) 1.22, 90% interval 1.17 to 1.28. Synonymous variants: 561 observed, 433.02 expected, observed/expected ratio (o/e) 1.3, 90% interval 1.21 to 1.39.
Gene-disease validity (ClinGen):
ClinGen rates the evidence that DNAAF2 causes each of these diseases.
primary ciliary dyskinesia 10 (autosomal recessive): Definitive.
Homologues: Orthologues: chimpanzee DNAAF2 (99% identical), macaque DNAAF2 (93% identical), dog DNAAF2 (74% identical), pig DNAAF2 (72% identical), rabbit DNAAF2 (68% identical), rat Dnaaf2 (66% identical), guinea pig DNAAF2 (64% identical), mouse Dnaaf2 (64% identical), tropical clawed frog dnaaf2 (33% identical), Drosophila melanogaster Nop17l (25% identical), zebrafish dnaaf2 (19% identical). Paralogues in human: PIH1D2 (8% identical), PIH1D1 (7% identical).
Diseases named in the same sentence as DNAAF2 in open-access papers:
DNAAF2 is named in the same sentence as 14 diseases in open-access papers, as found by Europe PMC text mining. Sharing a sentence is not in itself a finding about the gene and the disease. The quoted sentences say what the papers report.
male infertility (4 papers, 2020 to 2025). The inability of the male to effect fertilization of an ovum after a specified period of unprotected intercourse. "In Chinese adult patients, Sun et.at have identified two heterozygous variants, c.C156A [p.Y52X] and c.C26A [p.S9X], in the DNAAF2 gene, leading to defects in the outer dynein arms and inner dynein arms, thereby resulting in PCD with the manifestation of male infertility." (PMID 38053031, 2023). "In addition to mutations in DNAAF2, PCD-causing mutations in DNAAF1, DNAAF3 and DNAAF4 have been reported to cause male infertility, but the patient number is minimal." (PMID 31781811, 2020). "DNAL1 mutations are a very rare cause of PCD, but male infertility has been identified in a patient with a mutation in the dynein axonemal intermediate chain gene (DNAI2), which was also missing from the sperm tail in a male PCD patient with mutations in dynein axonemal assembly factor 2 (DNAAF2)." (PMID 31781811, 2020).
primary ciliary dyskinesia (3 papers, 2021 to 2024). A rare, genetically heterogeneous, primarily respiratory disorder characterized by chronic upper and lower respiratory tract disease. "Mutations in DNAAF2 were identified in individuals with primary ciliary dyskinesia (PCD, MIM # 244400), a motile ciliopathy characterized by recurrent respiratory infections, laterality defects and impaired fertility." (PMID 33635866, 2021).
Respiratory tract infection (1 paper, 2023). An infection of the upper or lower respiratory tract. "In 2008, two heterozygous variants c.C23A [pS8X] and c.1214-1215insACGATACCTGCGTGGC [p.G406Rfs89X] variants of DNAAF2 were first identified in two consanguineous families with PCD presented with recurrent respiratory tract infections, laterality defects and impaired fertility." (PMID 38053031, 2023).
DNAAF2 also shares sentences with these, for which no sentence is quoted: malaria (2 papers); bronchiectasis (1); Hydrocephalus (1); infection (1); Infertility (1); otitis media (1); parasitemia (1); pneumonia (1); scoliosis (1); sinusitis (1); ZIKV infection (1).